FOXP2 (forkhead box P2)
Diseases named in the same sentence as FOXP2 in open-access papers (continued):
Sharing a sentence is not in itself a finding about the gene and the disease.
language disorder (continued). "Aside from FOXP2, its downstream targets, and its binding partners, researchers have reasoned that candidate genes or genetic regions implicated in dyslexia may also represent good candidates for speech and language disorders." (PMID 20955937, 2010). "The Forkhead box P2 (FOXP2) is an evolutionary conserved transcription factor involved in the maintenance of neuronal networks, implicated in language disorders." (PMID 38828303, 2024). "In connection with this study is the study reviewing the evidence regarding FOXP2 in relation to the identification and evaluation of genetic evidence for language disorders." (PMID 36138610, 2022). "The genes PDE4D, FOXP2, and EML6 code for a cAMP phosphodiesterase, a transcription factor implicated in a speech and language disorder, and a microtubule associated protein, respectively." (PMID 36192459, 2022). "The discovery of the FOXP2 transcription factor, and its implication in a rare severe human speech and language disorder, has led to two decades of empirical studies focused on uncovering its roles in the brain using a range of in vitro and in vivo methods." (PMID 34260143, 2021). "In line with this, individuals from a family affected by speech and language disorders display a significant reduction of sumoylated FOXP2, supporting the pivotal role of FOXP2 sumoylation for the acquisition of these communication skills." (PMID 32719102, 2020). "FOXP2 promotes the nuclear translocation of POT1, but the mutated FOXP2(R553H) protein related to speech-language disorder, partially prevents it." (PMID 29725501, 2018). "The data presented here point to potential diversity in molecular mechanisms in FOXP2-related speech/language disorder." (PMID 27933109, 2016). "Concurrent with the present study, two further cases of probable FOXP2-related speech/language disorder were added to the DECIPHER database (patient IDs 271859 and 271246)." (PMID 27933109, 2016). "Heterozygous disruption of the FOXP2 gene, which encodes a member of the forkhead box (FOX) family of transcription factors, leads to a rare and severe form of speech and language disorder (MIM 605317 (gene), 602081 (disorder))." (PMID 26867680, 2016). "Very recently, while the current manuscript was under review, eight further families with potential FOXP2-related speech/language disorder have been newly described, based on sequencing data." (PMID 27933109, 2016). "FOXP2 mRNA is expressed in the developing human brain, in good concordance with anomalous sites identified by brain imaging in adult speech and language disorders." (PMID 26010484, 2015). "GWLA identified a region on chromosome 7q31 (maximum LOD score 6.62) that co-segregated with the language disorder in this particular family and has since been narrowed down to a causative mutation in the FOXP2 (forkhead box P2) gene (OMIM 605317)." (PMID 25411653, 2014). "Studies conducted on the FOXP2 gene, which is related to the speech-language disorder, unveiled the crucial role of the cerebellum and Purkinje cells in the pathogenesis of speech-language disorders." (PMID 23497090, 2013). "Another family member FOXP2 is involved in developmental speech and language disorders and directly regulates targets related to neural development and synaptic plasticity and developmental disorders like autism and schizophrenia." (PMID 23110997, 2012). "For example, the function of Foxp2, a transcription factor shown to be relatedto a human language disorder, is involved in pup isolation calls." (PMID 21408017, 2011).
language disorder (continued). "FOXP2 shows two important features as a convincing candidate gene for schizophrenia vulnerability: FOXP2 is the first gene related to a language disorder, and it has been subject to positive selection in the human lineage." (PMID 20649982, 2010). "Nevertheless there are strong evidence of the importance of the gene in development and some aspects of language including the fact that CNTNAP2, a downstream target of FOXP2 has been related also to language disorders." (PMID 20649982, 2010). "In addition, we evaluated risk genes for childhood apraxia of speech (CAS), the core phenotype of the FOXP2-related speech and language disorder." (PMID 41236144, 2025). "Moreover, TBR1 interacts with FOXP2, which is associated with speech and language disorders and the TBR1–FOXP2 interaction was shown to be abolished in patients with sporadic ASD." (PMID 37069342, 2023). "TBR1 interacts with the forkhead box protein P2 (FOXP2) to cause speech and language disorders." (PMID 36590912, 2022). "This provides some evidence that another gene associated with a language disorder is also related to these dynamic measures (FOXP2), but not another gene identified as a common monogenic cause of intellectual disability (FMR1)." (PMID 31639257, 2020). "While we cannot rule out that the p.N597H variant disrupts an aspect of FOXP2 function not tested here, subtle effects on protein function are unlikely to lead to a speech/language disorder of comparable severity to complete loss-of-function variants." (PMID 27933109, 2016). "Specifically, the authors' interest focuses on the upregulation of RARβ by FOXP2 in the striatum, where the primary pathology is located in people bearing a defective copy of FOXP2, known to give rise to language disorders (see Graham and Fisher, 2013 for review)." (PMID 25431551, 2014). "Mutations of FOXP2 and CNTNAP2 were linked to speech and language disorders and ASD." (PMID 23815876, 2013). "The FOXP2 gene is the first gene found to be involved in a speech and language disorder." (PMID 24765219, 2013). "Molecular studies of the effects of FOXP2 disruptions in individuals with a speech and language disorder show that its function is considerably affected, which may result in the abnormal development of important brain regions." (PMID 24765219, 2013). "Gene-targeting screens indicate that the FOXP2 protein is responsible for the downregulation of between 300 and 400 neural genes, many of which functionally represent good candidate genes for speech and language disorders." (PMID 20955937, 2010). "Based on its high sequence similarity to FOXP2, the capacity for the encoded proteins to form heterodimers, and evidence of their co-expression in some parts of the brain, the FOXP1 gene has been considered a candidate for being involved in speech and language disorders." (PMID 41159814, 2025). "For example, forkhead box P2 (FOXP2) and its downstream target gene contactin associated protein-like 2 (CNTNAP2) have been shown to be an important link in the networks of several speech and language disorders, including SLI, dyslexia, stuttering and dyspraxia." (PMID 25643770, 2015). "FOXP2 might be involved in the language disorder in patients with schizophrenia." (PMID 20649982, 2010). "Since receptive and expressive language disorders as well as ADHD have been considered common comorbidities of FASD, FOXP2 is a plausible candidate gene for developmental disorders induced by PAE." (PMID 36581877, 2022). "The story of the discovery of the FOXP2 (forkhead box P2) gene (OMIM#605317) and the elucidation of its involvement in a speech and language disorder begins with the study of a multigenerational British family known as the KE family." (PMID 24765219, 2013). "For example, no Neanderthal ancestry has been detected around the forkhead box protein P2 (FOXP2) gene, mutations of which are associated with language disorders." (PMID 30022013, 2018).
language disorder (continued). "Interestingly, among the genes highlighted by Sarachana and Hu (2013) one also finds candidates for language disorders, like CYP19A1, and several targets of FOXP2, like NTRK and A2BP1." (PMID 25431551, 2014).
autism (44 papers, 2009 to 2025). Persistent deficits in social interaction and communication and interaction as well as a markedly restricted repertoire of activity and interest as well as repetitive patterns of behavior. "We detected distinct expression patterns of autism risk genes, including FOXP2, highlighting the temporal regulation of excitatory and inhibitory neuronal lineages." (PMID 39363111, 2024). "FOXP2, a risk gene for both autism and developmental delay, was highly expressed at the end of the lineage, particularly in the postnatal stage." (PMID 39363111, 2024). "The Forkhead Box transcription factors FOXP1 and FOXP2 were found to be linked to speech and language disorders, and are among the risk genes for autism." (PMID 36388132, 2022). "FOXP2 is most well-known for its involvement in spoken language and both FOXP1 and FOXP2 have been associated with cognitive disorders such as schizophrenia and autism." (PMID 33319247, 2021). "Genes that have long been mentioned as involved in the causation of autism are FOXP2, RAY1/ST7, IMMP2L, and RELN genes at 7q22-q33." (PMID 32244359, 2020). "Single nucleotide polymorphisms (SNPs) in FoxP2 are also associated with language impairments in autism and schizophrenia." (PMID 29920554, 2018). "Another FoxP2 target, the Mef2C gene, is a transcription factor that has been linked to mental retardation and autism, and is known to negatively regulate excitatory synapse numbers." (PMID 29920554, 2018). "In this context it is worth pointing out that overexpression of FOXP2 in humans has been related to autism via MET, a putative risk factor for this condition." (PMID 26136701, 2015). "For example, haploinsufficiency of Shank3, CMIP, FOXP2 and Tsc2 has already been linked to the etiology and phenotypic characteristics of autism." (PMID 23451085, 2013). "Such overlaps are reflected in evidence for Darwinian positive selection, and recent human-specific changes in otherwise conserved amino acid positions, in genes such as AHI1, CNTNAP2 and FOXP2 that have been associated with risk of autism." (PMID 23639054, 2013). "It is located in a region of chromosome 7q that has been linked to autism in the past, and mutations in Foxp2 cause speech and language acquisition pathologies in humans." (PMID 24245670, 2013). "Chromosome 7q31 is a known autism susceptibility locus, particularly involving the language impairment of the disorder, therefore FOXP2 has been suggested as a potential ASD candidate gene." (PMID 22736078, 2012). "Additionally, we found that 31% of genes denoted as being most strongly linked to autism in the SFARI Gene database were significantly different between FOXP2+ cells in the control and knockdown groups." (PMID 33976169, 2021). "Additionally, large chromosome accidents comprising the FOXP2 region are functionally linked to autism (see section 5.2.3)." (PMID 29725501, 2018). "Importantly, its activities place FOXP2 at the center of an interactome hub regulating the expression of a cohort of other autism-linked genes." (PMID 29725501, 2018). "It would be important to investigate whether this is so in mammals, which may help to understand the association of FoxP2 in the development of the social deficits observed in autism." (PMID 27160258, 2017). "Collectively, these data suggest that HuR may regulate autism-associated Foxp1 and Foxp2 expression during neocorticogenesis." (PMID 27383233, 2016). "A knock-in mouse model expressing the pathogenic R552H FOXP2 mutation (corresponding to the human FOXP2 R553H mutation) exhibited an immature development of the cerebellum with impaired neuronal migration and autism-related deficits such as decreased ultrasonic vocalizations." (PMID 27199730, 2016). "Characterizing the vocal behavior of animal models will be critical in evaluating the role of autism-susceptibility and other (e.g. FOXP2) genes implicated in speech and language learning in an ongoing effort to test therapeutics for social communication disorders." (PMID 26018425, 2015).
autism (continued). "Interestingly, autism-related mutations in FOXP2 diminished the suppressive effect on DISC1 transcription." (PMID 23083465, 2012). "Furthermore, CNTNAP2, one of the SNPs whose expression is regulated by FOXP2, is associated with impairments of language development in several syndromes, such as autism and SLI." (PMID 23115634, 2012). "In literature, several autism models with mutations in Foxp2, Nlgn4, and Tsc2 exhibit reduced USV." (PMID 21203536, 2010). "Finally, MET transcription is regulated by FOXP2, a further autism risk-gene." (PMID 23083465, 2012). "Pregnant mice treated with a sublethal dose of the human influenza virus gave birth to animals with a significant upregulation of the schizophrenia and autism related gene Forkhead box P2 (Foxp2) in the hippocampus at P35 and P56." (PMID 35628292, 2022). "Mutations in FOXP2 in humans have been consistently associated with Autism Spectrum Disorders (ASD), and as such, FOXP2 is ranked category 1 (high confidence) in the SFARI autism gene database." (PMID 34421555, 2021). "It is believed that FOXP1interacts with FOXP2 and CNTNAP2, both implicated in speech disorders and autism." (PMID 22102821, 2011). "In earlier work, based on low-throughput shotgun sequencing of human FOXP2-ChIP fragments, we identified a FOXP2-bound element in the first intron of CNTNAP2 (contactin-associated-protein-like-2) a gene implicated in language impairments and autism." (PMID 21765815, 2011). "Because both the Il1rapl2+ L5 IT neurons and the Foxp2+ L6 CT neurons in the mPFC have the most number of differentially expressed GWAS genes for bipolar disorder and autism, they might be involved in regulating aspects of social behaviors." (PMID 40267197, 2025). "Even FOXP2, often considered the “language gene” and in OMIM recognized as specific Speech-Language disorder-1 (OMIM; # 602081), has been linked to other neurodevelopmental disorders, like intellectual disability and autism." (PMID 38298611, 2024). "Although more and larger sequencing studies will be informative, based on the current evidence, the Simons Foundation Autism Research Initiative (SFARI GENE) ranks FOXP2 as a category 1, “high confidence” ASD gene (following the highest confidence category of “Syndromic”)." (PMID 34421555, 2021). "Social communication deficits are central to ASD diagnosis, and both language dysfunction and autism may be influenced through downstream regulation by FOXP2 key target genes that ultimately impact circuit wiring." (PMID 29725501, 2018). "It is worth mentioning here that FOXP2 protein dramatically down-regulates CNTNAP2, a strong candidate gene for autism, whereas OXT gene encodes the neuropeptide binding the oxytocin receptor (OXTR), another strong candidate gene for autism." (PMID 20885821, 2010). "Epidemiological studies rank FOXP2 with a score of 3 on the SFARI autism scale, an intermediate “suggestive evidence” among stronger scores (Syndromic; 1: high confidence; 2: strong candidate) and weaker ones (4: minimal evidence; 5: hypothesized but untested; 6: unsupported)." (PMID 29725501, 2018). "A thoroughly studied example of a gene repressed by FOXP2, CNTNAP2, has been implicated in disorders such as specific language impairment and autism, among others, which sheds some light on the mechanism through which FOXP2 may be influencing speech and language." (PMID 24765219, 2013). "Additionally, people with isolated mutations of FOXP2 do not show any signs of ASD even though FOXP2 is involved in pathways relevant to autism." (PMID 22736078, 2012). "Various genes enriched in modern humans are disease-relevant genes like CHD8 and CPEB4 in autism spectrum, HTT in Huntington’s disease, FOXP2 in language impairment." (PMID 36550402, 2022).
autism (continued). "However, more recent evidence suggests that the language deficits are more directly related to a developmental impairment of motor brain regions, rather than to social behavior, and several recent reports conclude that Foxp2 does not contribute to autism susceptibility." (PMID 24245670, 2013). "For example, Foxp2, a forkhead/winged helix (FOX) transcription factor, is found in seven of the nine autism databases used." (PMID 24245670, 2013). "No enrichment for autism-candidate genes or Foxp2 targets was observed for the ‘high-confidence', ‘rare and novel' or de novo CNVs in independent cases." (PMID 25585696, 2015).